GLP1R (glucagon like peptide 1 receptor)
Diseases named in the same sentence as GLP1R in open-access papers (continued):
Sharing a sentence is not in itself a finding about the gene and the disease.
Headache (2 papers, 2024 to 2025). Cephalgia, or pain sensed in various parts of the head, not confined to the area of distribution of any nerve. "GLP-1R agonists have been tested for their ability to promote weight loss and reduce headache in patients with IIH." (PMID 38997662, 2024). "The therapeutic scope of GLP-1R agonists is expanding beyond traditional metabolic targets, highlighting its potential for headache and pain disorders." (PMID 38997662, 2024).
Hypercalcemia (2 papers, 2024 to 2026). An abnormally increased calcium concentration in the blood. "Despite these intriguing connections, there is a notable paucity of large-scale studies specifically examining the association between GLP-1R agonist use and the risk of hypocalcemia or hypercalcemia." (PMID 39201039, 2024). "This study aimed to investigate the association between GLP-1R agonist use and the risk of hypocalcemia and/or hypercalcemia, as well as other clinical outcomes." (PMID 39201039, 2024). "Hypercalcemia is rarely reported in the literature and has previously been reported in patients taking GLP-1R agonists with concomitant thiazide diuretic or exogenous calcium supplement." (PMID 42226819, 2026).
hyperthyroidism (2 papers, 2022 to 2025). Overactivity of the thyroid gland resulting in overproduction of thyroid hormone and increased metabolic rate. "This case report describes the rare adverse effect of hyperthyroidism secondary to the use of liraglutide, a glucagon-like peptide-1 receptor agonist." (PMID 40949169, 2025).
Hypokalemia (2 papers, 2025). An abnormally decreased potassium concentration in the blood. "Glucagon-like peptide-1 receptor agonists are not known to cause hypokalemia." (PMID 40772190, 2025).
ischemic colitis (2 papers, 2025 to 2026). Inflammation of the colon due to colonic ischemia resulting from alterations in systemic circulation or local vasculature. "Colon ischemia may be associated with decreased oral intake caused by glucagon-like peptide-1 receptor agonists (GLP-1RAs), which can result in systemic hypotension and, ultimately, ischemic colitis." (PMID 40667509, 2025).
kidney cancer (2 papers, 2025). Primary or metastatic malignant neoplasm involving the kidney. "It found a significant reduction in the risk of several cancers among GLP1R agonist users compared to insulin users, but no clear benefit compared to metformin, and even a potential increased risk of kidney cancer." (PMID 39777709, 2025).
kidney injury (2 papers, 2021 to 2025). Trauma to the kidney. "Exenatide, a Glucagon-like peptide-1 receptor agonist(GLP-1RA), protects against high-fat diet (HFD)-induced kidney injury." (PMID 34434166, 2021).
LEPR deficiency (2 papers, 2023 to 2024). "The treatments include hormone replacement therapy with recombinant leptin for subjects with LEP deficiency, the MC4R agonist setmelanotide for LEPR deficiency, and glucagon-like peptide-1 receptor agonists for subjects with MC4R deficiency." (PMID 37659411, 2023).
lipodystrophy (2 papers, 2024 to 2025). A congenital or acquired disorder characterized by abnormal loss or redistribution of the adipose tissue in the body. "This provides important insights regarding the benefits of GLP-1R agonists for treating lipodystrophy, informing more widespread use to improve the health of individuals with this condition." (PMID 38745956, 2024). "Appropriate monitoring will be necessary for GLP-1R agonists use in the treatment of patients with lipodystrophy." (PMID 38745956, 2024). "Another key potential advantage of GLP-1R agonists for lipodystrophy patients is the availability of both long acting and oral GLP-1R agonists." (PMID 38745956, 2024). "Reports of the effects of GLP-1R agonists in individuals with inherited lipodystrophies are currently limited to only 3 case studies, and these examine FPLD but not CGL patients." (PMID 38745956, 2024). "As the first study to examine in detail the effects of GLP-1R agonists in a pre-clinical model of lipodystrophy, we provide a valuable basis for future patient studies to ultimately relieve the suffering of these patients." (PMID 38745956, 2024). "As such, examining the effect of GLP-1R agonists in a model of lipodystrophy is required before widespread adoption of its use in patients." (PMID 38745956, 2024). "Hence, it is critical to gain insights specifically into the mechanisms underpinning any effects of GLP-1R agonists in preclinical models of lipodystrophy to better understand their use for treating patients with these conditions." (PMID 38745956, 2024). "Here we performed the first detailed investigation of the effects of a glucagon like peptide-1 receptor (GLP-1R) agonist in lipoatrophic diabetes, using mice with generalised lipodystrophy." (PMID 38745956, 2024).
liver dysfunction (2 papers, 2025). "Nonetheless, the potential protective effects of liraglutide (LIRA), a GLP-1R agonist, against atorvastatin (ATO)-induced liver dysfunction have not been fully elucidated." (PMID 40711038, 2025).
metastatic disease (2 papers, 2023 to 2026). "The lack of GLP-1R expression was associated with a metastatic disease (p < 0.001)." (PMID 37894845, 2023). "Forty-eight of the forty-nine (98%) non-metastatic tumours expressed GLP-1R, while one non-metastatic, multiple endocrine neoplasia type 1 (MEN1)-related tumour and all three of the metastatic tumours lacked GLP-1R expression." (PMID 37894845, 2023).
neuropathic pain (2 papers, 2024 to 2025). Chronic pain caused by damage to nerve fibers. "GLP-1 receptor (GLP-1R) agonists, like liraglutide, have shown analgesic effects by modulating pain hypersensitivity in animal models of inflammatory and neuropathic pain." (PMID 38997662, 2024).
peritonitis (2 papers, 2022 to 2025). Inflammation of the peritoneum (tissue that lines the abdominal wall and covers most of the organs in the abdomen). "Here, we assessed the role of GLP-1R in MSU crystal-induced peritonitis by using wild-type (WT) and GLP-1R knockout (KO) mice." (PMID 35154099, 2022). "GLP-1R-deficient macrophages have reduced migration properties and overexpress IL-6 without any changes in IL-1β expression, as shown in monosodium urate (MSU)-induced peritonitis in mice." (PMID 40592472, 2025). "GLP-1R−/− mice with MSU-induced peritonitis have significantly reduced M2 macrophage infiltration/recruitment in comparison to M1 macrophages, which are the same in WT and GLP-1R−/− mice with no changes in neutrophil infiltration." (PMID 40592472, 2025).
rectal cancer (2 papers, 2024 to 2026). A primary or metastatic malignant neoplasm that affects the rectum. "Weak evidence indicated the connections of GLP1R, GPD2, and PRKAB1 with anal carcinoma, cardia cancer, ICC, and rectum cancer." (PMID 38504335, 2024).
retinal ischemia (2 papers, 2024 to 2025). A ischemic disease that involves the retina. "Agents that are known to modulate microglia and macrophages, including minocycline and the GLP-1R agonist exendin-4, inhibited inner blood-retinal barrier breakdown after retinal ischemia-reperfusion." (PMID 39182142, 2024).
tauopathies (2 papers, 2020 to 2021). "Studying the role of GLP-1R agonists in additional mouse models with different features of AD including tauopathies and how ameliorating the microglia and reactive astrocytes phenotype lead to reduce Aβ deposition is warranted in future investigations." (PMID 33902708, 2021).
uterine cancer (2 papers, 2025). Primary or metastatic malignant neoplasm involving the uterine corpus and/or the cervix. "For instance, the influence of GLP1R expression on estrogen or progesterone receptor-positive tumors might explain differential survival outcomes in cancers like breast and uterine carcinomas." (PMID 39777709, 2025).
airway hyperresponsiveness (1 paper, 2023). "GLP1R agonists activate the cyclic AMP-dependent protein kinase A in the human airway and relax airway smooth muscle cells, thus proving GLP1 receptors to be potential targets for treating airway hyperresponsiveness." (PMID 37056543, 2023).
allergic asthma (1 paper, 2025). A asthma with a basis in a pathological type I hypersensitivity reaction. "A flow cytometer-based study has indicated the presence of GLP-1R+neutrophils (10%) and eosinophils (5%) in healthy human adults and the GLP-1R+ eosinophil population decreases to 2% in patients with allergic asthma." (PMID 40592472, 2025).
allergic contact dermatitis (1 paper, 2022). An inflammatory skin condition caused by an immune response to direct contact between the skin and an allergen. "Finally, we demonstrated the presence of GLP-1R+CD4+ T cells in skin from patients with allergic contact dermatitis." (PMID 36010663, 2022). "Finally, to exclude that GLP-1R expression in T cells was just an in vitro phenomenon, we tested whether GLP-1R+CD4+ T cells could be detected in skin from patients with allergic contact dermatitis to nickel." (PMID 36010663, 2022). "In this study, we demonstrate that a sub-population of activated human T cells, and especially iTreg cells, express the GLP-1R, and that GLP-1R+CD4+ T cells are found in the dermis of both non-lesional and lesional skin from patients with allergic contact dermatitis." (PMID 36010663, 2022).
anal carcinoma (1 paper, 2024). "GLP1R was tentatively associated with anal carcinoma (OR = 49.160; 95% CI: 1.648–1.466 × 103; P-value = 0.025) and cardia cancer (OR = 25.073; 95% CI: 5.064-124.149; P-value < 0.0001)." (PMID 38504335, 2024). "Meantime, prior studies suggested that thiazolidinediones and glucagon-like peptide-1 analogues were connected with cancer risk, which could further validate our findings that PPARG and GLP1R were associated with increased anal carcinoma and cardia cancer risk." (PMID 38504335, 2024). "Strong evidence suggested colocalization between DPP4, GLP1R, ABCC8/KCNJ11, and anal carcinoma." (PMID 38504335, 2024).
aortic valve calcification (1 paper, 2023). "Thus, identifying GLP-1R-independent mechanisms will be critical to fully elucidate how GLP-1 ameliorates aortic valve calcification." (PMID 37754815, 2023). "Taken together, these findings pinpoint a previously unidentified role of the GLP-1/GLP-1R axis in the pathogenesis of CAVD and indicate that liraglutide may serve as a potential therapeutic drug for preventing aortic valve calcification." (PMID 37754815, 2023).
atrial flutter (1 paper, 2023). A disorder characterized by an electrocardiographic finding of an organized, regular atrial rhythm with atrial rate of 240-340 beats per minute. "Glucagon-like peptide-1 receptor agonists (GLP-1 RA) could diminish AF and atrial flutter in diabetic patients, but these actions could not be confirmed in meta-analysis." (PMID 37109205, 2023).
bacterial sepsis (1 paper, 2025). "Another study has indicated that the loss of GLP-1R in Phox2b+ cells present in nodose ganglion (NG), midbrain, hindbrain and visceral sensory neurons impairs glucose homoeostasis, which can be altered during different stressful conditions, such as bacterial sepsis." (PMID 40592472, 2025).
Blindness (1 paper, 2024). Blindness is the condition of lacking visual perception defined as a profound reduction in visual perception. "In this study, semaglutide (a long-acting GLP-1R agonist) showed an unexpectedly higher rate of severe DR complications (i.e., vitreous hemorrhage, blindness, or conditions requiring treatment with an intravitreal agent or photocoagulation)." (PMID 38694495, 2024).
brain tumors (1 paper, 2024). "Studies of the glucagon-like peptide-1 receptor (GLP-1R) expression across various human tumors have found it predominantly in specific endocrine, embryonal, and brain tumors, but it is notably scarce or absent in most carcinomas." (PMID 39335195, 2024).
breast tumor (1 paper, 2025). "This specific study supports multiple plausible mechanisms associated with the inhibitory effect of GLP-1R agonists on breast tumor progression, strongly suggesting the potential to enhance immune-modulating therapies." (PMID 41178720, 2025). "GLP-1R mRNA is detected in some cancers, including pancreatic, thyroid, and invasive breast tumor tissues." (PMID 41178720, 2025).
cerebral (1 paper, 2018). "Intracellular cAMP levels are also raised in exendin-4-treated post-transient middle cerebral artery occlusion as a result of increased GLP1R expression." (PMID 30165597, 2018).
cervical cancer (1 paper, 2021). A primary or metastatic malignant neoplasm involving the cervix. "Moving forward, it will be important to unravel the basic mechanisms involved in the relationship between the co-expression of PSMA2 and GLP-1R in T2D-linked cervical cancer, and their downregulation by Exendin-4." (PMID 33714887, 2021). "In this context, it should be noted that the knockdown of GLP-1R in human and mouse cervical cancer cell lines led to the corresponding downregulation of PSMA2, implying a direct effect, independent of the glucose-lowering function of Exendin-4." (PMID 33714887, 2021). "For example, whether the relationship between PMSA2 and GLP-1R expression is specific to cervical cancer, or common across other T2D-related cancer types, remains unclear." (PMID 33714887, 2021).
cervical squamous cell carcinoma (1 paper, 2025). A squamous cell carcinoma arising from the cervical epithelium. "Conversely, higher GLP1R expression is linked to poorer survival outcomes in cervical squamous cell carcinoma, lung squamous cell carcinoma, stomach adenocarcinoma, and uterine corpus endometrial carcinoma." (PMID 39777709, 2025). "Conversely, higher GLP1R expression correlates with poorer survival outcomes in cancers such as cervical squamous cell carcinoma, lung squamous cell carcinoma, stomach adenocarcinoma, and uterine corpus endometrial carcinoma." (PMID 39777709, 2025). "On the other hand, the association between high GLP1R expression and decreased survival in cancers like cervical squamous cell carcinoma and lung squamous cell carcinoma suggests that GLP-1R activation may promote tumor progression in these contexts." (PMID 39777709, 2025).
cholestasis (1 paper, 2022). Impairment of the bile flow caused by obstruction within the liver, or outside the liver in the bile duct system. "GLP-1R was found to be expressed in bile duct cells, and the expression was increased in cholestasis." (PMID 36386208, 2022).
delirium (1 paper, 2024). A disorder characterized by confusion; inattentiveness; disorientation; illusions; hallucinations; agitation; and in some instances autonomic nervous system overactivity. "This may suggest that the perioperative use of GLP‐1R agonists in cardiac surgeries and beyond may offer some advantages over other drugs, notably in preventing delirium." (PMID 38155547, 2024).
diabetic encephalopathy (1 paper, 2023). A brain disease that is characterized by functional impairment of cognition, cerebral signal conduction, neurotransmission and synaptic plasticity, and underlying structural pathology associated with diabetes. "Exendin-4 (Ex-4), a widely used glucagon-like peptide-1 receptor agonist drug in the treatment of T2D, has been demonstrated the therapeutic effects on diabetic encephalopathy (DE)." (PMID 37667187, 2023).
fibrosarcoma (1 paper, 2023). A malignant mesenchymal fibroblastic neoplasm affecting the soft tissue and bone. "For the Ser/Thr kinases, those identified belong mainly to the rapidly accelerated fibrosarcoma (RAF) and the MAPK/ERK families, both previously shown to play pivotal roles downstream of GLP‐1R activation." (PMID 37039251, 2023).
gallbladder cancer (1 paper, 2025). "A recent meta-analysis covering 90 studies found no excess risk for hepatic, biliary tract, pancreatic, colorectal, or gallbladder cancers in people using GLP-1R therapies." (PMID 41178720, 2025).
gastric diseases (1 paper, 2024). "As of now, there is limited clinical evidence surrounding the association of the use of novel second-line anti-diabetic drugs (SGLT2I, DPP4I and glucagon-like peptide-1 receptor agonist (GLP1a) on different types of gastric diseases." (PMID 38856768, 2024).
gastric neoplasm (1 paper, 2026). A benign or malignant neoplasm involving the stomach. "Whether the risk of gastric neoplasm is modified by newer glucose-lowering therapies-dipeptidyl peptidase-4 inhibitors (DPP4is), glucagon-like peptide-1 receptor agonists (GLP1RAs), and sodium-glucose cotransporter 2 inhibitors (SGLT2is)-remains uncertain." (PMID 41898482, 2026).
Gastrointestinal obstruction (1 paper, 2025). "Known patient aspiration risk factors include BMI, previous gastric/esophageal surgery, gastrointestinal obstruction, delayed gastric emptying, and use of glucagon-like peptide-1 receptor agonists." (PMID 41583815, 2025).
graft versus host disease (1 paper, 2025). An immune system disorder that occurs after allogeneic hematopoietic stem cell transplant and is a reaction of donor immune cells against host tissues. "Notably, in a mismatched graft-versus-host disease (GvHD) model, C57BL/6J recipients of donor BALB/c T cells developed small-intestinal inflammation, and donor T cells within the small-intestinal epithelium expressed functional GLP-1R." (PMID 41178710, 2025).
Hyperammonemia (1 paper, 2026). An increased concentration of ammonia in the blood. "This study aims to evaluate the therapeutic potential of exendin-4, a glucagon-like peptide-1 receptor agonist, in mitigating BBB disruption and inflammation induced by hyperammonemia." (PMID 42222506, 2026).
hypertensive chronic kidney disease (1 paper, 2019). "Our data on the renal GLP-1R expression in HS animals and the increase in urine sodium concentration following DPP4 inhibition indicate a role of this system also in the pathobiology of hypertensive chronic kidney disease." (PMID 30774748, 2019).
Hypocalcemia (1 paper, 2024). An abnormally decreased calcium concentration in the blood. "GLP-1R agonist use was associated with a reduced risk of hypocalcemia (2.7% vs. 5.5%, p < 0.001; RR 0.49, 95% CI: 0.44–0.55) and improved clinical outcomes, particularly in cardiovascular health." (PMID 39201039, 2024). "The observed 51% reduction in hypocalcemia risk across all GLP-1R agonists is a novel finding with important clinical implications." (PMID 39201039, 2024). "The mechanism underlying this protection against hypocalcemia is not fully understood but may be related to the known effects of GLP-1R agonists on bone metabolism and calcium homeostasis." (PMID 39201039, 2024).
kidney transplant (1 paper, 2024). A surgical procedure in which one or both kidneys from a donor are implanted into a recipient. "Evidence supporting glucagon-like peptide-1 receptor agonists (GLP-1RAs) in kidney transplant recipients (KTRs) remains scarce." (PMID 38410684, 2024).
learning disabilities (1 paper, 2025). "GLP-1R-deficient mice exhibit learning disabilities, and this can be reversed by introducing the GLP-1R gene into the hippocampus." (PMID 40171533, 2025).
malocclusion (1 paper, 2024). "Furthermore, regarding submandibular gland GLP-1R, a decrease in immuno-positive areas of GLP-1R in a malocclusion model of rats with extracted teeth has been reported, which is similar to the results of decreased immuno-positive areas of GLP-1R observed in this study due to T2DM." (PMID 39479116, 2024).
nephritis (1 paper, 2025). Inflammation of renal tissue. "Glp1r–/– mice with nephrotoxic serum–induced nephritis showed enhanced renal infiltration of neutrophils and CD4+ T cells, along with increased proinflammatory cytokine gene expression in the spleen and lymph nodes." (PMID 41178710, 2025).
Neurodegeneration (1 paper, 2020). Progressive loss of neural cells and tissue. "Growing evidences have reported stimulation of glucagon‐like peptide‐1 (GLP‐1)/GLP‐1 receptor (GLP‐1R) signalling axis provides neuroprotection in experimental models of neurodegeneration disease." (PMID 32573108, 2020).